CD4 (CD4 molecule)
Diseases named in the same sentence as CD4 in open-access papers (continued):
Sharing a sentence is not in itself a finding about the gene and the disease.
tumor (continued). "Relying on CTLs to eradicate tumors may be not always be effective, even when they have sufficient CD4 “help,” particularly when faced with tumor cells that have downregulated tumor antigen/s and/or surface MHC class I molecules." (PMID 24955376, 2014). "Similar results were seen in tumor-bearing mice in our CD4 depletion model (data not shown)." (PMID 25119341, 2014). "Immunotherapy in the EMT6 tumor model led to increased induction of direct killing (by CD8+ effector cells) using splenocytes from treated mice, along with increased cytokine production in vitro-both effects were attenuated in mice receiving anti-CD4 treatment in vivo." (PMID 25409195, 2014). "The finding that naïve CD4+ T cells could initiate rejection of a MHC II negative tumor indicated that host cells expressing MHC class II molecules were responsible for the presentation of Id to CD4+ T cells." (PMID 24782871, 2014). "Accordingly, the CD8:Treg and CD4:Treg ratios were higher in treated tumors (p = 0.01), suggesting that preoperative therapy may specifically deplete immunosuppressive cell types in the PDA tumor microenvironment." (PMID 24794217, 2014). "Cytotoxic CD4+ targeting viral antigens and alloantigens have been described previously, but in these models, the influence of Tregs on effector CD4+ T-cell activity was not investigated but the tumor or the pathogen was eliminated by adoptive transfer of effector CD4+ T cells." (PMID 22890822, 2013). "In order to do justice to their contributions in tumor settings, other Foxp3 non-expressing, peripherally induced CD4+ regulatory cells, specifically Tr1 cells, will be discussed separately as such in one section and the rest of our discussion will focus on Foxp3+ peripherally converted iTregs." (PMID 23874336, 2013). "Tumor-challenged mice were treated and on day 5 post treatment, mice from each treatment group were sacrificed and the cells from the spleen and draining lymph node were stained, using direct immunofluorescence, for the presence of Tregs as defined by their co-expression of CD3, CD4 and Foxp3." (PMID 23840786, 2013). "Taken together, these data demonstrate that CD4+ T cell help is not required for the therapeutic immune responses generated by SA-4-1BBL-based vaccination and the lack of CD4+ T cell role is independent of TAAs and tumor models used in this study." (PMID 24066030, 2013). "However, the CD4+ T cells alone, even in the absence of Treg suppression, were not sufficient to abrogate tumor progression but the Treg removal was performed by using anti-CD25 antibodies and depletion of Tregs was incomplete." (PMID 22890822, 2013). "Accumulating evidence suggests that select CD4 effector T cell subsets may have a more “direct” role in inhibiting tumor growth and progression that are independent of their more “indirect” helper activities." (PMID 23533029, 2013). "However, this does not appear to be the case with IL-35, as tumor-infiltrating CD4+Foxp3+ nTregs had higher levels of suppression then infiltrating Foxp3− iTr35 cells." (PMID 24151492, 2013). "In addition, the significance of regulatory T cells (Tregs) in inhibiting tumor-specific CD4+ T-cell responses during tumor rejection in vivo has not been defined." (PMID 22890822, 2013). "Furthermore, IFN-γ production from CD8+ cells, but not from CD4+ cells, was shown to be critical for the anti-tumor effect of the anti-TIM-3 treatment." (PMID 24348481, 2013). "Importantly, to investigate whether CD4+ and CD8+ T cells infiltrated in RdB/IL23/p35-infected tumor tissues are IFN-γ- and TNF-α-co-expressing T cells, FACS analysis was carried out on lymphocytes isolated from tumor." (PMID 23844018, 2013). "Depletion of CD8+, but not CD4+ T cells resumed tumor growth." (PMID 23671644, 2013).
tumor (continued). "However, recent studies have uncovered additional functions and roles for CD4 T cells, some of which are independent of other lymphocytes, that can not only influence and contribute to tumor immunity but paradoxically promote tumor growth and progression." (PMID 23533029, 2013). "Recently, it was demonstrated that CD4+ T cell help not only promotes CTL expansion in peripheral lymphoid organs, but is also required for the recruitment of low avidity CD8+ T cells into tumor microenvironment and augmentation of cytolytic function via up-regulation of granzyme B." (PMID 24066030, 2013). "A CD4+ cell-restricted blockade of TGF-ß signaling in mice expressing a dominant negative version of the receptor resulted in eradication of TGF-ß expressing lymphoma or metastatic B16F10 melanoma and has established a firm link between TGF-ß and tumor immune tolerance." (PMID 24133490, 2013). "The CD4:CD8 ratio did not change after transduction or exposure to KIT+ tumor (not shown)." (PMID 23433424, 2013). "Interestingly, the Authors found a negative correlation between CD8/CD4(+/+) infiltration and both tumor depth and TNM stage and in multivariate analysis the CD8/CD4(+/+) infiltration was confirmed as an independent prognostic factor of survival." (PMID 23950747, 2013). "Furthermore, IFN-gamma ELISPOT analyses reveal that the increase in cancer immunity was mediated by anti-tumor specific CD4+ T-helper cells, without concomitant induction of CD8+ cytotoxic T cells." (PMID 23768240, 2013). "No significant change in the ratio of total CD8+ to CD4+ T cells was observed at day 14 post-tumor implant whereas a significant increase was achieved in animals treated with a single dose of 1 mg/kg 4-1BB mAb (p = 0.0193) at day 22 post-tumor implant." (PMID 24829750, 2013). "Because the main property of MDSC is to contrast the immunosurveillance mechanisms of CD8+ and CD4+ T lymphocytes, the balance between T cells and MDSC within the cancer microenvironment may be a crucial cornerstone in dictating the fate of the neoplastic disease." (PMID 23616948, 2013). "This exposure provoked a contact dependent uptake of tumor derived cytosol by lymphocytes – even in CD4+ T cells and murine B cells – which could not be detected after incubation of lymphocytes with healthy cells." (PMID 24205259, 2013). "Efficient inhibition of tumor growth was recently shown to involve not only defined cell death and clearance mechanisms by CD8+ cytotoxic T lymphocytes and natural killer cells, but also the induction of tumor cell senescence by interferon-γ and TNF producing CD4+ T-helper 1 cells." (PMID 23987103, 2013). "Furthermore, we observed that tumor-derived Tim-3+CD4+ cells, but not their Tim-3− counterparts, suppressed production of IFN-γ by T cells." (PMID 23526963, 2013). "Subsequently spleen, lymph nodes and bone marrow were checked for BM185 cells but only in the spleen could numerous tumor cells be detected (data not shown) which was combined with the appearance of green-fluorescent CD4+ T cells." (PMID 24205259, 2013). "Interestingly, Tim-3+Foxp3+ CD4 T cells were preferentially distributed in the tumor nest, rather than the peritumoral stroma." (PMID 23526963, 2013). "Thus, DAC-induced CTL responses, but not CD4+ T cell responses are mainly responsible for the tumor regression." (PMID 23671644, 2013). "Moreover, tumor-derived Tim-3+ CD4 T cells, but not tumor-derived Tim-3− CD4 T cells, significantly suppressed the proliferation of autologous CD8+ T cells in vitro." (PMID 23526963, 2013). "Alternatively, the expression of inhibitory molecules on the surface of tumor cells could promote the expansion and accumulation of nonresponsive anergic T cells or CD4(+)CD25(+)Foxp3(+) T-regulatory cells (Tregs) within the tumor microenvironment." (PMID 23533456, 2013).
tumor (continued). "Within the CD3+CD4+population, an increase in anti-tumorigenic Th1 cells may suppresstumors in COX-2MECKO mice; however, greater activity of Th2lymphocytes and/or Treg would be expected to promote tumor growth." (PMID 24004819, 2013). "In contrast to this, all the CD4+ T cell-deficient mice transferred with CTLs alone or CTLs together with Th(pMHC-I-/-), Th(CD40L-/-) or Th(IL-2-/-) cells failed to get protection, and had considerably increased tumor colonies of varying sizes in lungs." (PMID 23785406, 2013). "This suggests that Tregs in the drLNs can inhibit the development of effector cells such as cytotoxic CD4+ and CD8+ T cells, whereas Tregs in the tumor itself may have dual functions of controlling tumor-promoting inflammation on one hand but suppressing local effector T-cell responses on the other." (PMID 22890822, 2013). "Moreover, several studies have defined additional roles for CD4 T cells, some of which are independent of other lymphocytes, that influence and/or contribute to tumor immunity during carcinogenesis." (PMID 23533029, 2013). "Interestingly, calcarea carbonica-exposed tumor explants not only failed to induce T cell apoptosis but also increased the percent of CD4+ and CD8+ T cells." (PMID 24053127, 2013). "Furthermore, pre-treatment of MSC with IFNγ (within a moderate range) upregulates MHC-I and II expression and improves antigen phagocytosis and presentation capabilities, thereby stimulating CD4 and CD8 T-cell proliferation and generation of anti-tumor CD8+ cytotoxic T-lymphocytes (CTLs)." (PMID 23162801, 2012). "Quantification of the number of CD4+, CD8+ and FOXP3+ T-lymphocytes in progressive disease indeed confirmed a lower number of positive cells located on the endometrial-myometrial border (EM), at the edge of the tumor (Tumor Edge) and within the tumor (Intratumoral)." (PMID 22295114, 2012). "However, administration of the anti-CD4 antibody did not affect the anti-tumor activity of the triple combination (data not shown)." (PMID 22295090, 2012). "Another study demonstrates that anti-GITR treatment together with CD8+ cells in SCID recipient mice is sufficient to reject the tumor, while CD4+ transferred cells are not, although CD4+ cells play a central role in helping the functions of CD8+, NK and B cells." (PMID 22654588, 2012). "However, induction of tumor-specific CD4+ T cell responses does not assure intraocular tumor elimination." (PMID 23060881, 2012). "The only immunohistochemical study focusing on immune response to tumor ablation with IRE used immunohistochemistry to show that there was no recruitment of immune cells such as CD4+, CD8+ T lymphocytes, macrophages, activated antigen presenting cells (APCs) and dendritic cells after 72 hours." (PMID 23139816, 2012). "Of note, the MHC class II antigen, which is known to be subject to regulation by IFN-γ, was significantly upregulated in the tumor following HCA587 protein vaccine treatment (data not shown), which may render the tumor more vulnerable to CD4+ T cells attack." (PMID 23071764, 2012). "The results concerning other studied CD molecules as CD3 or CD19 and CD45 (data not shown) were no significant in all treated cancers; in the case of CD4 slightly decreased values were registered (as only two cases of each tumour were studied, these observations not be statistically valuable)." (PMID 22400112, 2012). "However, in the absence of SH2D2A, the numbers of GB113+ CD4+ SP thymocytes of tumor resistant mice were significantly higher than in the wild type mice." (PMID 23144743, 2012). "In addition to stimulating tumor cell proliferation, stromal activation and angiogenesis, TDSFs promote the maturation/recruitment of myeloid-derived suppressor cells (MDSCs) that inhibit the tumor-specific functions of CD8+ and CD4+ T lymphocytes." (PMID 22762146, 2012).
tumor (continued). "We examined whether the TLR9 ligand, TLR9 agonist could activate TLR9-expressing cells in vivo and analyzed the number and phenotype of splenic CD4+ T helper cells, CD8+ T cells, B cells, pDCs and NKDCs in tumor-bearing mice, 24 hours after TLR9 agonist administration (10 mg/kg body weight, s.c)." (PMID 22666458, 2012). "As CD4 T cells are often shown to be essential for tumor rejection, we wanted to determine whether CD4 T cells control the recruitment of CD8 T cells indirectly through modifying the local tumor environment." (PMID 22911764, 2012). "However, it is not clear if the increase of CD4+CD25+ Tregs in situ is correlated with the upregulated expression of IDO in tumor cells." (PMID 22110525, 2011). "These in vivo studies suggested that naïve Foxp3-negative CD8 and CD4 T cells could not be induced to express Foxp3 after they have infiltrated and been exposed to signals within the tumor microenvironment." (PMID 22112546, 2011). "First, in-vitro co-incubation of WSX1-positive tumor cells reduces the number of T cells and induces a significant increase in caspase 8 and caspase 9 activation as well as an increase in late apoptosis markers mainly in CD8, and to a lesser extent, in CD4 T cells." (PMID 21559505, 2011). "Meth-A cells transfected with the human IL-17 gene can induce tumor-specific antitumor immunity by augmenting the expression of major histocompatibility complex (MHC) class I and II antigens; this antitumor immunity may be mediated by CD4+ and CD8+ T cells." (PMID 21943203, 2011). "In addition to CD4+ Tregs also CD8+CD28- Tregs could be isolated from peripheral blood, tumor tissue and metastatic lymph nodes of CRC patients." (PMID 24212779, 2011). "Moreover, it does not appear that the patient's age, gender, CD4 cell count, tumor type, tumor size, nor location of their tumor had a noticeable impact on their outcome." (PMID 21437186, 2011). "Because the antigen specificity of Treg is largely unknown, it is unclear if the ability of Treg to inhibit anti-tumor responses is related or not to the presence/prevalence among them of tumor-antigen specific CD4+ T cells." (PMID 21829534, 2011). "Thus, CD8 and CD4 transgenic T cells in these animal models failed to undergo peripheral induction of Foxp3 in a tumor microenvironment." (PMID 22112546, 2011). "Similarly, defective proliferation of tumor-specific CD4+ and CD8+ T cells in tumor-draining LN, which may reflect presentation of tumor antigen by DC migrating from the tumor to the LN, was not improved in these mice." (PMID 21390236, 2011). "In addition, we assessed whether APCs such as DCs could capture and process antigens derived from dead STEAP expressing tumor cells (freeze-thaw cell lysates) and present the STEAP epitope to the CD4 T-cell clones." (PMID 22053850, 2011). "Higher percentages of CD4/Foxp3 positive cells were found in spleens and LN from nontumor-bearing Pmel/Foxp3EGFP mice compared to C57BL/6 Foxp3EGFP mice (overall average 25% compared with 12%), but there was no additional Foxp3 enrichment among CD4 TIL in tumor-bearing animals." (PMID 22112546, 2011). "Importantly, they showed that immune CD4+ Th cells can induce protective antitumor responses in naive mice injected with parental nontransfected tumor cells." (PMID 22110523, 2011). "In that model, BALB/c mice were depleted of different immune cells before, or during, immunization with Her2-MPyVLPs, and there we could show that CD4+ and CD8+ cells could act separately to protect mice from tumor outgrowth, while depletion of both subsets of cells completely abrogated protection." (PMID 21858228, 2011). "Moreover, depletion of CD8+ and NK cells did not alter the efficacy of the vaccine whereas depletion of CD4+ cells eliminated its anti-tumor activity." (PMID 21385454, 2011).
tumor (continued). "This approach has been employed previously as a cancer immunotherapy studies which showed that TCR α and β-chains could be introduced into CD4+ and CD8+ T cells in order to create a tumor-directed Teff cell population that upon adoptive transfer destroyed pre-existing tumor mass." (PMID 20668510, 2010). "Interestingly, the tumor bearing condition did not suppress miR-17-5p expression by CD4+ T cells in STAT6-/- mice." (PMID 20167088, 2010). "Indeed, CD4+ and CD8+ splenocytes (SPCs) derived from wild type C57BL/6 mice bearing B16 subcutaneous tumors expressed lower levels of miR-17-5p when compared with those derived from non-tumor bearing mice." (PMID 20167088, 2010). "Thus, they efficiently activate and expand tumor-reactive CD8+ CTLs and CD4+ T cells." (PMID 21076523, 2010). "The lack of known CD4 epitopes or antigens has limited studies into the association between KSHV-specific CD4 responses and the control of KSHV or the development (and subsequent resolution) of KSHV-related neoplasms." (PMID 22331985, 2010). "However, mice lacking β2-microglobulin or perforin were not protected implying that tumour protection was mediated by MHC class-I restricted cytotoxic T cells independent of CD4+ T cells." (PMID 20657846, 2010). "Moreover, tumour protection was lost after combined depletion of CD4+ and CD8+ cells, which should not have had a more profound effect on antibody titres than depletion of CD4+ cells alone." (PMID 20657846, 2010). "Depletion of CD8+ but not CD4+ cells led to a complete abrogation of the tumor immunity." (PMID 21197271, 2010). "Although it has been shown that CD4+ T cells may be sufficient by themselves to eliminate tumor cells, it is more often the case that both CD4+ and CD8+ T cells are required for effective tumor cell elimination because most tumor cells only express HLA class I molecules." (PMID 20385003, 2010). "Furthermore, the majority of studies into this population have focused on the adverse effects of regulatory CD4+ T cells, thus creating a negative reputation for these cells in tumor immunology." (PMID 21076522, 2010). "Since CMT.64 cells do not express MHC class II molecules, a major function of CD4+ T cells may be to support CD8+ T-cell responses to tumor cells or through a cytokine release mechanism to accumulate and activate effector cells." (PMID 19629186, 2009). "However, the role of CD4 T cells in directly killing tumor cells or clearing tumors, independent of CD8 T cells, is less well-studied." (PMID 19707583, 2009). "In agreement with the Th2 skew observed in circulating CEA specific CD4+ T cells, immunohistochemical analysis of tumor infiltrating lymphocytes showed a significantly higher number of GATA-3+ (Th2) compared to T-bet+ (Th1) lymphoid cells, supporting a Th2 skew also at the tumor site." (PMID 19798410, 2009). "The use of class II peptides derived from the TAAg (rather than exogenous helper antigen such as keyhole limpet haemocyanin) opened the possibility of CD4+ T cell-induced anti-tumour effects, which have been demonstrated in murine model systems with class II negative tumour cells." (PMID 19298672, 2009). "S100+ and CD1a+ DCs were found in tumor epithelium, in parallel with intraepithelial CD4+ or CD8+ T-cell infiltration and suggested increased disease-free survival, while HLA class II+ cells were observedin the stromal compartment, correlated with adversed outcome of the tumor." (PMID 19009040, 2008). "In all patients, high tumour grade was positively associated with negative hormonal receptor status (P<0.001), high Ki-67 labelling index (P<0.001) and high expression of CD34+ (P<0.01), CD68+ (P<0.05), CD4+ (P<0.05) and CD8+ (P<0.05) T lymphocytes." (PMID 18797461, 2008).